DOK4 (docking protein 4)
Description:
DOK proteins are enzymatically inert adaptor or scaffolding proteins. They provide a docking platform for the assembly of multimolecular signaling complexes. DOK4 functions in RET-mediated neurite outgrowth and plays a positive role in activation of the MAP kinase pathway (By similarity). Putative link with downstream effectors of RET in neuronal differentiation. May be involved in the regulation of the immune response induced by T-cells.
Synonyms: IRS-5; IRS5; FLJ10488
Tractability: PROTAC: ubiquitination databases record sites on it; its protein half-life has been measured.
Gene: Protein-coding gene on chromosome 16 (57,471,917 to 57,487,382, reverse strand). Ensembl gene ENSG00000125170.
Subcellular location (Human Protein Atlas): Cytosol
Pathways (Reactome):
Developmental Biology: RET signaling
Gene Ontology:
Molecular function: protein binding; signaling adaptor activity
Biological process: cell surface receptor protein tyrosine kinase signaling pathway
Cellular component: cytosol; mitochondrion
Genetic constraint (gnomAD): Loss-of-function variants: 26 observed, 39.42 expected, observed/expected ratio (o/e) 0.66, 90% interval 0.48 to 0.92. The upper end of that interval is the gene's LOEUF score, 0.92, which puts it in group 3 of 6, group 1 being the genes least tolerant of losing a copy. Missense variants: 392 observed, 455.42 expected, observed/expected ratio (o/e) 0.86, 90% interval 0.79 to 0.94. Synonymous variants: 179 observed, 185.52 expected, observed/expected ratio (o/e) 0.96, 90% interval 0.85 to 1.09.
Homologues: Orthologues: macaque DOK4 (100% identical), pig DOK4 (99% identical), guinea pig DOK4 (99% identical), dog DOK4 (98% identical), mouse Dok4 (98% identical), rat Dok4 (98% identical), rabbit DOK4 (93% identical), chimpanzee DOK4 (90% identical), zebrafish dok4 (75% identical), tropical clawed frog dok4 (62% identical), Caenorhabditis elegans rog-1 (18% identical), Drosophila melanogaster Dok (17% identical), and 1 more. Paralogues in human: DOK6 (63% identical), DOK5 (56% identical), DOK1 (23% identical), DOK2 (21% identical), DOK3 (21% identical), FRS3 (14% identical), FRS2 (13% identical).
Diseases named in the same sentence as DOK4 in open-access papers:
DOK4 is named in the same sentence as 13 diseases in open-access papers, as found by Europe PMC text mining. Sharing a sentence is not in itself a finding about the gene and the disease. The quoted sentences say what the papers report.
breast carcinoma (3 papers, 2020). "We previously reported that a 4-gene score derived from the tumor expression of DOK4, HCCS, PGF, and SHCBP1 genes is associated with tumor aggressiveness and can be considered as a potential predictive biomarker for breast cancer." (PMID 32650578, 2020). "As we previously reported, the four-gene score has reflected cell proliferation in breast cancer by measuring gene expressions of DOK4, HCCS, SHCBP1, and PGF; it was of interest to investigate the distribution of the score in other types of cancer in The Cancer Genome Atlas (TCGA) project." (PMID 33291601, 2020). "DOK4 is a positive regulator of the mitogen-activated protein kinase (MAPK) pathway, and it undergoes phosphorylation by the RET tyrosine kinase, whose over-expression is observed in estrogen receptor (ER)-positive breast cancer." (PMID 32370309, 2020).
non-small cell lung carcinoma (2 papers, 2020). A group of at least three distinct histological types of lung cancer, including non-small cell squamous cell carcinoma, adenocarcinoma, and large cell carcinoma. "The expression of DOK4 gene was reported to regulate chromatin remodeling in non-small-cell lung cancer." (PMID 33291601, 2020). "DOK4 was also reported to be both up- and downregulated in non-small cell lung cancer with experiments pointing toward an epigenetic mechanism." (PMID 32370309, 2020).
acute myeloid leukemia (1 paper, 2020). Acute myeloid leukemia (AML) is a group of neoplasms arising from precursor cells committed to the myeloid cell-line differentiation. "DOK4 was recently identified as a biomarker for poor prognostic outcomes in acute myeloid leukemia and involvement in nerve, breast, and other cancer cell lines." (PMID 32370309, 2020).
Ductal Carcinoma in situ (1 paper, 2020). "Indeed, DOK4 expression was increased by knockdown of miR-182 and miR-183 in Ductal Carcinoma in situ." (PMID 32370309, 2020).
fibrosarcoma (1 paper, 2020). A malignant mesenchymal fibroblastic neoplasm affecting the soft tissue and bone. "Finally, DOK4 was highly expressed in canine peripheral nerve sheath tumors that can be used to differentiate it from fibrosarcomas." (PMID 32370309, 2020).
Hodgkins lymphoma (1 paper, 2023). A heterogeneous group of malignant lymphoid neoplasms of B-cell origin characterized histologically by the presence of Hodgkin and Reed-Sternberg (HRS) cells in the vast majority of cases. "Previous study also showed that the chemotherapy-sensitive Hodgkin lymphoma patients had frequent gains of 16q13, a chromosomal region known to house genes that regulate T-cells trafficking or NF-ĸB activation (CX3CL1, CCL22, CCL17, DOK4, and IL10)." (PMID 37153002, 2023).
neuroblastoma (1 paper, 2007). Neuroblastoma (NB) is the most common solid, extracranial childhood tumor. "Dok4 was shown to regulate GDNF/Ret dependent neurite outgrowth in neuroblastoma cells." (PMID 18021428, 2007).
pancreatic cancer (1 paper, 2020). "DOK4 has been reported as a potential biomarker for prognostic outcomes in several cancers, but not in pancreatic cancer." (PMID 33291601, 2020).
renal cell carcinoma (1 paper, 2014). "Up regulation of DOK4 is also noted in renal cell carcinoma." (PMID 24387052, 2014).
cancer (4 papers, 2011 to 2020). A tumor composed of atypical neoplastic, often pleomorphic cells that invade other tissues. "Downstream of tyrosine kinase-4 (Dok-4), a membrane-localized adapter protein, is an inhibitor of tyrosine kinase signaling in cancer." (PMID 32456226, 2020).
DOK4 also shares sentences with these, for which no sentence is quoted: tumor (3 papers); brucellosis (1); gastric cancer (1).